INS (insulin)
Diseases named in the same sentence as INS in open-access papers (continued):
Sharing a sentence is not in itself a finding about the gene and the disease.
Glucose intolerance (continued). "The results show that multiple infusions of allogeneic BM-MSCs are able to promote prolonged decrease in glucose intolerance and apoptosis in pancreatic islets and increase in insulin sensitivity in hyperglycemic HFD fed mice." (PMID 25923733, 2015). "Our results suggest that components of Eugenia extract favourably modulate the insulin/glucose process, decreasing the glucose intolerance." (PMID 26783951, 2015). "Insulin clearance has been reported to be negatively correlated with the progression of glucose intolerance." (PMID 26623647, 2015). "Next, we determined if the reduced Tcf7l2 expression in beta cells and the subsequent worsening of glucose intolerance are coupled with changes in plasma insulin content." (PMID 25398947, 2015). "RG108 also ameliorated systemic glucose intolerance and insulin signalling cascades in liver and muscle that are major target organs of adiponectin." (PMID 26139044, 2015). "First, in our previous study, we have shown that transgenic mice are glucose intolerant and that the glucose intolerance progressed to decreased insulin sensitivity and reduction in insulin production when the mice were fed a HFD." (PMID 26136681, 2015). "The role of insulin clearance in glucose intolerance has thus far been studied, however, the role of insulin clearance remains controversial." (PMID 26623647, 2015). "MT-tg female mice also showed glucose intolerance and reduced insulin secretion during GTT, but much less severe than those observed in males." (PMID 26335571, 2015). "At 8 weeks of age, MT-tg male mice developed severe glucose intolerance, and MT-tg impaired glucose stimulated insulin secretion (GSIS) during GTT." (PMID 26335571, 2015). "Genome perturbation and damage have also been postulated to compromise beta-cell function in RIP-Cre mice, leading to glucose intolerance and partial impairment in insulin secretion." (PMID 26046525, 2015). "We herein show that CGA/Cr formulation reverses body weight gain in addition to insulin and glucose intolerance in mice fed a high-fat diet." (PMID 26045713, 2015). "The 48-week old male mice in the IR group developed DM status and exhibited: 1) decreased BW, 2) higher fasting glucose levels, 3) lower serum insulin levels, 4) glucose intolerance and 5) glycosuria." (PMID 25799429, 2015). "Consistent with this, LMP7−/− mice showed improvement of glucose intolerance and insulin sensitivity." (PMID 26515636, 2015). "This hepatic phenotype of glucose intolerance along with modifications to genes involved in gluconeogenesis, insulin signalling and lipid synthesis were also seen in the male ArKO mice as previously published." (PMID 26317527, 2015). "Recent work from Guy Rutter's laboratory has shown that a beta cell-specific knock-out of Tcf7l2 leads to decreased beta cell volume, decreased insulin secretion, and subsequent glucose intolerance in mice fed high fat diet." (PMID 25398947, 2015). "In sum, expression of the RIP::IGF-1 transgene partially corrected glucose intolerance, rescued insulin sensitivity, partially ameliorated the aberrantly heightened gluconeogenic production, and reduced fasted blood glucose content in female GHR-KO mice." (PMID 25244225, 2014). "HOMAIR score, calculated as a marker of glucose intolerance, indicated that 60%-fed mice were insulin resistant compared to 10%-fed mice (P = 0.03)." (PMID 25072025, 2014). "Heterozygote mice development is normal; however, when challenged with a high fat diet, they develop severe obesity, glucose intolerance, and impaired insulin release." (PMID 24812634, 2014). "In female mice, 12 weeks of a HFD induced glucose intolerance and elevated plasma insulin levels compared to female mice fed the SCD." (PMID 25375135, 2014). "The previous PANKO mixed model did show impaired insulin secretion, resulting in glucose intolerance." (PMID 25217499, 2014).
Glucose intolerance (continued). "Recent data suggest that maternal HFD feeding during lactation affects hypothalamic neurodevelopment ultimately leading to glucose intolerance, and that hypothalamic insulin signaling contributes to this effect." (PMID 24684305, 2014). "In conclusion, the present results indicate that the HFD-induced glucose intolerance-prone (SDG-P) mice had a hereditary defect in insulin secretion as compared with the glucose intolerance-resistant (SDG-R) mice." (PMID 24454742, 2014). "We show that FGF19-induced signaling in the hypothalamus ameliorated glucose intolerance by improving insulin sensitivity." (PMID 24567901, 2014). "Studies have confirmed that high fructose feeding causes alterations in glucose and lipid metabolism, a substantial decrease in peripheral insulin sensitivity, glucose intolerance, and hypertension." (PMID 25006525, 2014). "Intra-abdominal fat is resistant to insulin, giving rise to hyperlipidemia, glucose intolerance, hypertension and atherosclerosis." (PMID 24977121, 2014). "This large quantities of fructose consumptions leads to lipogenesis and triglyceride accumulation, which in turn results in insulin sensitivity reduction and hepatic insulin resistance/glucose intolerance." (PMID 25587319, 2014). "Its inactivation results in immature beta cells with lowered insulin expression and secretion and severe glucose intolerance." (PMID 25628604, 2014). "Intraperitoneal and oral glucose tolerance tests in Sidt2 knockout mice indicated glucose intolerance and decreased serum insulin level." (PMID 23776622, 2013). "Glucose intolerance, altered insulin content and skewed lipid profile of the experimental animals, resemble the hallmarks of this model that actually persist in a later stage of human TIIDM patients." (PMID 23840254, 2013). "On the other hand, knockdown of TAp73 resulted in an increase in insulin sensitivity and protection from glucose intolerance in mice on a high-fat diet, possibly because of the positive effects of ROS on insulin signaling." (PMID 23954639, 2013). "Although ZFs were hyperinsulinemic with elevated basal glycemia, when challenged with a bolus injection of glucose, only to a meagre glucose-stimulated insulin release was observed, suggesting glucose intolerance." (PMID 24454978, 2013). "Cdkal1-deficient β-cells have impaired glucose-induced insulin secretion, and Cdkal1 knockout mice develop glucose intolerance due to aberrant insulin synthesis." (PMID 24204302, 2013). "We found that OXT treatment significantly improved glucose intolerance and fasting blood insulin levels of mice, and this effect was observed without involving body weight change since the experimental duration was only an overnight period." (PMID 23700406, 2013). "Defective first phase insulin secretion in adult mice results in mild glucose intolerance compared to floxed controls." (PMID 24204824, 2013). "Catechin showed enhanced insulin secretion in presence of glucose and significant reversal of glucose intolerance in high-fat-diet-induced diabetic mice." (PMID 23936668, 2013). "Both salsalate and salicylate treatment significantly improved glucose intolerance and insulin sensitivity, accompanied by reduced SeP mRNA and protein expression in HFD-fed rats and db/db mice, respectively." (PMID 23825542, 2013). "The phenotype of glucose intolerance and impaired insulin secretion reported for the TG2−/− mouse was from a lineage derived from an undefined mix of both 129/SvJ and C57BL/6J (B6;129) parental genomes." (PMID 23717413, 2013). "Pancreas-specific STAT3-KO mice exhibit glucose intolerance and impaired insulin secretion in vivo, along with microvascular alterations in the pancreas." (PMID 23923060, 2013). "These had normal body weight (data not shown) and fasting blood glucose levels but exhibited mild glucose intolerance and increased insulin sensitivity." (PMID 24315372, 2013).
Glucose intolerance (continued). "Several reports have found diet-dependent glucose intolerance and insulin secretion abnormalities in SLC30A8 knockout mice." (PMID 23334806, 2013). "Our data indicated that EPO treatment significantly reduced the body weights and the levels of fasting blood glucose and serum insulin, and improved glucose intolerance in the HFD-fed mice." (PMID 23326455, 2013). "The NA + STZ-treated rats show glucose intolerance, increased serum TG, and decreased serum insulin levels, indicating NIDDM-like condition." (PMID 23840254, 2013). "At this early time point, the mice still displayed euglycaemia and a tendency towards glucose intolerance, in the presence of normal plasma insulin." (PMID 23197416, 2013). "C57BL/6 mice have a high insulin secretory capacity and with age they will increase this to reduce the impact of peripheral low-grade inflammation on glucose intolerance." (PMID 24369539, 2013). "The roles of PICK1 and ICA69 in insulin trafficking provide the basis to understand the glucose intolerance and insulin maturation defects found in PICK1 and ICA69 KO mice." (PMID 23630453, 2013). "Accompanying the secretory defect, glucose intolerance was reported in 2 studies while in another study there was decreased plasma insulin and increased glucose tolerance." (PMID 23750248, 2013). "By 21 weeks of HFD, CD44KO mice remained considerably less glucose intolerance and insulin sensitive than WT mice." (PMID 23505504, 2013). "Administration of 0.5% EBN reduced the HFD-induced increase in body weight, total cholesterol level, and fatty liver and improved the impaired fasting glucose level, blood insulin content, and glucose intolerance." (PMID 23690860, 2013). "Although the effect on weight gain ceased, whey alleviated glucose intolerance, improved insulin sensitivity and reduced plasma cholesterol." (PMID 23940754, 2013). "In this study, we showed that whey reduces body weight gain, alleviates glucose intolerance, improves insulin sensitivity and reduces plasma cholesterol in mice fed a high-fat diet." (PMID 23940754, 2013). "Nonetheless, obese LFD-fed IL-1RI−/− mice exhibited only moderate glucose intolerance, negligible adipose inflammation, and preservation of adipose insulin sensitivity compared with age-matched HFD counterparts." (PMID 23921145, 2013). "In the present study, the inability of insulin secretion to compensate for a decrease in insulin sensitivity resulted in glucose intolerance." (PMID 23675523, 2013). "In parallel, using streptozotocin-induced diabetic mouse model, we found that treatment with oxytocin or its analogs reduced the magnitude of glucose intolerance through improving insulin secretion." (PMID 23700406, 2013). "As mice fed KD for 6 days already exhibited impaired insulin sensitivity, resulting in glucose intolerance, we examined blood glucose, insulin, and glucagon levels in wild-type and Fgf21 knockout mice fed NC or KD for 6 days." (PMID 23874946, 2013). "These mice exhibit glucose intolerance and impaired insulin secretion in vivo, but normal insulin secretory function in response to glucose challenge in isolated islets." (PMID 23923060, 2013). "Taken together, these studies suggest that butyrate can be protective of high fat-induced glucose intolerance and insulin insensitivity." (PMID 23363995, 2012). "The combination of glucose intolerance and inappropriate low insulin levels during the glucose tolerance test led us to further examine the functional β-cell mass in pdx1CRE/- COUP-TFIIFl/Fl mice." (PMID 22292058, 2012). "Insulin secretion in response to an i.p. glucose challenge was markedly compromised in the mutant mice, suggesting that glucose intolerance is due to the inadequate supply of insulin from insufficient beta-cell mass." (PMID 22870272, 2012).
Glucose intolerance (continued). "Two groups have looked in parallel at an exon 1 knockout mouse line maintained as separate colonies and both found effects on zinc accumulation by β-cells, glucose intolerance and insulin secretion that were diet, age, and genetic background dependent." (PMID 22996130, 2012). "In pancreatic β-cells, loss of mTOR signaling with p70S6K has been shown to lead to hypoinsulinemia, glucose intolerance, insulin insensitivity to glucose secretion, and a decrease in β-cell size." (PMID 22545721, 2012). "The glucose intolerance in RenTgMK mice in the presence of normal fasting glucose levels and low insulinemia, a feature that is a rather typical hallmark of increased insulin sensitivity, could be due to decreased insulin production/secretion and/or increased insulin clearance." (PMID 23308073, 2012). "Studies in mice suggest that ID1 is a negative regulator of insulin secretion, playing an essential role in the etiology of glucose intolerance, insulin secretory dysfunction, and β-cell dedifferentiation under conditions of increased lipid supply." (PMID 22607048, 2012). "Glucose intolerance (iAUC increased by ∼60%) and blunted insulin-stimulated hepatic Akt and GSK3β phosphorylation (∼40–60%) were found in both feeding conditions (p<0.01 vs Con, assessed after 1 week)." (PMID 22355328, 2012). "When maintained on an HFD, Mgat2+/+ mice showed an expected increase in blood glucose, insulin, and total cholesterol levels as well as in glucose intolerance." (PMID 22698140, 2012). "In summary, our data demonstrate that transgenic hepatic overexpression of renin leads to glucose intolerance, decreased fat mass, hypoinsulinemia, and hypotriglyceridemia, with normal systemic insulin sensitivity." (PMID 23308073, 2012). "Since OA treatment attenuates the glucose intolerance with similar blood insulin levels as T2D-Veh mice, the improved glucose tolerance and glycemia in T2D-OA mice is probably due to improved insulin sensitivity of the peripheral tissues." (PMID 22860063, 2012). "Following vhlh inactivation in beta-cells, sustained activation of HIF-target gene expression under normoxic conditions tended to increase insulin secretion at low glucose while reducing the maximal GSIS with consequent development of glucose intolerance." (PMID 22235342, 2012). "The effects of 5% butyrate (wt/wt) supplementation on the prevention of glucose intolerance and insulin insensitivity induced by high fat feeding was also observed in C57BL/6N mice." (PMID 23363995, 2012). "One potential explanation for these observations is that elevated basal AKT and JNK activities desensitize the response to insulin, leading to glucose intolerance, and that reduced PTEN function boosts AKT signaling thus improving glucose handling." (PMID 22412882, 2012). "Our results demonstrate that elevated circulating Ang II due to renin overexpression leads to glucose intolerance, but with consistently lower levels of plasma insulin." (PMID 23308073, 2012). "At the same time, impaired insulin production would result in a pronounced glucose intolerance in a manner that is consistent with the phenotype described for the HFD mice exposed to 50 ppm As." (PMID 21592922, 2011). "The insulin-sensitizing adipokine adiponectin is another important factor involved in glucose intolerance." (PMID 21569357, 2011). "Studying a cohort of girls with premature adrenarche, whose androgen profiles are reminiscent of PCOS, Ibanez observed increased insulin levels and glucose intolerance throughout maturation." (PMID 21899727, 2011). "It must be pointed out that in response to an oral glucose load the plasma insulin increased more in ML mice than in controls, suggesting an adaptation to glucose intolerance and decreased insulin sensitivity." (PMID 21698161, 2011). "This was coupled with a slight worsening of glucose intolerance that was likely attributable to defective hepatic insulin response." (PMID 21980475, 2011).
Glucose intolerance (continued). "We show that in mice with short telomeres, insulin secretion is impaired and leads to glucose intolerance despite the presence of an intact β-cell mass." (PMID 21423765, 2011). "This suggests that the mild glucose intolerance of ksr1-/- mice reflects a role for KSR1 in insulin secretion." (PMID 22206009, 2011). "During euglycaemic–hyperinsulinaemic clamping, the infusion of GlcN in rodents producing plasma GlcN concentrations of between 800 and 1200 μmol/L results in glucose intolerance and insulin insensitivity 32,37." (PMID 21218504, 2011). "Glucose intolerance and impaired brain response to insulin were observed in SE offspring, and this was aggravated by maternal HFD consumption." (PMID 22076142, 2011). "Young normal weight TS women show significant glucose intolerance in spite of normal insulin secretion during hyperglycaemic clamping and normal insulin sensitivity." (PMID 21406078, 2011). "Mice deficient in the zinc-sensor GPR39, which has been demonstrated to protect cells against endoplasmatic stress and cell death in vitro, display moderate glucose intolerance and impaired glucose-induced insulin secretion." (PMID 22164158, 2011). "Here we show that short telomeres are sufficient to recapitulate the glucose intolerance and insulin secretion defects which occur in the early stages of human age-related diabetes." (PMID 21423765, 2011). "The glucose intolerance, lower insulin levels, and defective glucose-stimulated insulin release were also present in a second strain of mice with short telomeres [mTR−/− fourth generation (G4) mice] on the C57BL/6 background." (PMID 21423765, 2011). "We here describe a direct causal link between impaired telomerase activity and impaired insulin secretion as well as glucose intolerance in Terc-/- G4 mice." (PMID 20876939, 2010). "Despite disturbed insulin secretion, the mice appeared generally healthy with only mild glucose intolerance and normal insulin sensitivity." (PMID 20126668, 2010). "Suppression of ROS in obese type 2 diabetic mice restores β-cell function and insulin sensitivity, leading to amelioration of glucose intolerance." (PMID 20182627, 2010). "Morioka and colleagues further confirm that mice with specific disruption of leptin receptor in pancreatic β cells develop more severe glucose intolerance when fed a high-fat diet due to impaired insulin secretion from β cells." (PMID 21113299, 2010). "Lxrβ-/- mice display lower amounts of adipose tissue on one hand and glucose intolerance (due to impaired glucose-induced insulin secretion) on the other." (PMID 20939869, 2010). "Basal and insulin-stimulated glucose uptake was reduced in isolated skeletal muscle, and the transgenic animals developed glucose intolerance despite being protected from diet-induced obesity." (PMID 20847941, 2010). "When pregnant mice were treated with BPA on GD9–GD16, they developed glucose intolerance and elevated levels of plasma insulin, triglycerides, glycerol, and leptin compared with control pregnant mice." (PMID 20488778, 2010). "Islet morphometric studies demonstrated decreased β-cell mass suggesting that this was a major component responsible for altered Insulin secretion and glucose intolerance in caCnRIP mice." (PMID 20689817, 2010). "We find that these animals develop glucose intolerance and impaired insulin secretion due to impaired beta-cell regeneration." (PMID 20876939, 2010). "Deletion of synaptotagmin-7, a calcium sensor in insulin secretion, resulted in glucose intolerance and impaired insulin secretion in synaptotagmin-7 KO mice, even though the KO mice exhibited normal resting and fed glucose levels." (PMID 21085706, 2010). "For example, mice that specifically overexpress PDE3B in pancreatic β-cells demonstrate glucose intolerance and impaired insulin response to glucose and glucagon-like peptide-1 (GLP-1)." (PMID 19262749, 2009).